RNU7-1 (RNA, U7 small nuclear 1)
Synonyms: U7.1; AGS9; RNU7
Gene: Small nuclear RNA gene on chromosome 12 (6,943,816 to 6,943,878, forward strand). Ensembl gene ENSG00000238923.
Gene-disease validity (ClinGen):
ClinGen rates the evidence that RNU7-1 causes each of these diseases.
RNU7-1-related type 1 interferonopathy (autosomal recessive): Moderate. Any type 1 interferonopathies in which the cause of the disease is a variation in the RNU7-1 gene.
Homologues: Paralogues in human: RNU7-2P (90% identical), RNU7-3P (89% identical), RNU7-6P (89% identical), RNU7-10P (87% identical), RNU7-11P (87% identical), RNU7-19P (87% identical), RNU7-4P (87% identical), RNU7-7P (87% identical), RNU7-9P (87% identical), RNU7-12P (86% identical), RNU7-13P (86% identical), RNU7-14P (86% identical), and 143 more.
Diseases named in the same sentence as RNU7-1 in open-access papers:
RNU7-1 is named in the same sentence as 1 disease in open-access papers, as found by Europe PMC text mining. Sharing a sentence is not in itself a finding about the gene and the disease.
RNU7-1 shares sentences with these, for which no sentence is quoted: Aicardi-Goutières Syndrome (5 papers).